ORAI1 (ORAI calcium release-activated calcium modulator 1)
Diseases named in the same sentence as ORAI1 in open-access papers (continued):
Sharing a sentence is not in itself a finding about the gene and the disease.
breast cancer (continued). "In breast cancer, elevated ORAI1 and lower ORAI3 levels are features of basal breast cancers, and in prostate cancer cells, reduced SOCE confers resistance to some apoptotic pathways." (PMID 34573310, 2021). "From the functional point of view, SOCE in MCF7 is mediated by STIM1, STIM2, and Orai3, in contrast to other breast cancer subtypes, such as TNBC cells, where SOCE is entirely dependent on STIM1 and Orai1." (PMID 34439314, 2021). "The increased proliferation of breast cancer cells (MCF-7 wild-type and SPCA2-overexpressed MCF-10A) is induced by Ca2+ influx from SPCA2-stimulated Orai1." (PMID 33806911, 2021). "For example, STIM1 was originally isolated as a tumor suppressor and was validated as such in an independent screen, yet in the context of several cancers including breast cancer STIM1 and Orai1 are crucial for metastasis." (PMID 34069353, 2021). "In addition, Ca2+ signaling is known to regulate migration of normal and breast cancer cells and certain mechanosensitive Ca2+ channels, particularly the Transient Receptor Potential (TRP) and Orai1 families, are overexpressed in breast cancer and associated with poor clinical prognosis." (PMID 33490070, 2020). "In breast cancer cells, the interplay of SK3 and Orai1 has been demonstrated to lead to constitutive Orai-dependent, but STIM1-independent Ca2+ entry." (PMID 33333945, 2020). "Given the ability of NCS‐1 silencing to phenocopy the effects of ORAI1 silencing in MDA‐MB‐231 breast cancer cells, we explored the possibility that NCS‐1 silencing‐mediated suppression of unstimulated Ca2+ influx was due to reduced expression of ORAI1." (PMID 31647602, 2020). "For example, in breast cancer, glioblastoma, renal cell carcinoma, and esophageal squamous cell carcinoma (ESCC), STIM1 and Orai1 are reported to contribute to proliferation, migration, or both." (PMID 32575848, 2020). "In the breast cancer cell lines MCF7 and MDA-MB-231 cells, the silencing of Orai3 and Orai1 expressions reduced cell proliferation and tumorigenic properties." (PMID 31973006, 2020). "After showing the overexpression of Kv10.1, Orai1 and SPCA2 in similar area of breast cancer tissue, we here demonstrate that SPCA2 has a role in the collagen 1 induced survival of BC cells and that this happens through the regulation of the Kv10.1-Orai1 complex." (PMID 30718673, 2019). "Here, we sought to define ORAI1 and ORAI3 expression in breast cancer cell lines of different molecular subtypes and assess the potential role and regulation of ORAI3 in basal breast cancer cells." (PMID 30754719, 2019). "The role of AC8 in cell migration is not specific to TNBC cells, as similar results were observed in the luminal breast cancer MCF7 cell line, which exhibits some common features with the MDA-MB-231 cell line, such as AC8 and Orai1 overexpression." (PMID 31652779, 2019). "To define levels of ORAI1 and ORAI3 in breast cancer molecular subtypes, we assessed RNA sequencing (RNA-Seq) data from the TCGA breast cancer database (845 tumors)." (PMID 30754719, 2019). "In contrast to ORAI1, the enrichment of ORAI3 in clinical breast cancer samples is largely unexplored." (PMID 30754719, 2019). "It has been demonstrated that SOCE in estrogen receptor (ER)-positive breast cancer cells is mediated by Orai3 and STIM2/STIM1, whereas SOCE in ER-negative breast cancer cells mostly depends on the canonical Orai1/STIM1 pathway." (PMID 31252656, 2019). "Breast cancer cells from the different subtypes undergo remodeling of the expression of specific molecular SOCE components, including Orai1, Orai3, TRPC1 and even TRPC6." (PMID 30558192, 2018). "In contrast, in the non-tumoral MCF10A cell line, treatment with CO-OCS was unable to alter the expression of STIM1 or Orai1, which indicates that protein glycosylation plays a relevant role in STIM1 expression and breast cancer cell migration." (PMID 30558192, 2018).
breast cancer (continued). "Altered expression of STIM1 and Orai1, key molecular components of store operated calcium entry (SOCE) pathways have been reported in cervical cancer, breast cancer, and esophageal cancer." (PMID 29861863, 2018). "For instance, pharmacological inhibition of SOCE with SKF or silencing of ORAI1 and STIM1 was shown to inhibit cell migration in MDA-MB-231 breast cancer cells." (PMID 30034631, 2018). "The process of migration and invasion are an important step in the metastasis of breast cancer, and these processes can be regulated by a variety of factors such as BRMS1, E-cadherin, CXCL12, MMP9, Orai1, Stim1, TGF-β, and VEGF." (PMID 29316690, 2018). "In addition, depletion of Ca2+ from the ER may drive tumor growth by inducing Ca2+ influx through the plasma membrane, as the expression of the SOCE canonical components STIM1 and ORAI1 is augmented in various cancer types, including breast cancer, glioblastoma, melanoma, and esophageal carcinoma." (PMID 25710007, 2015). "Based on our recent findings in mammary tumor cells, we evaluated a potential role for SPCA2 in eliciting Ca2+ entry into the lactating mammary secretory cells, by interaction with Orai1 channels." (PMID 23840669, 2013). "Consistent with the overexpression of Orai1 in breast cancer, SPCA2 was overexpressed in human breast cancer cell lines and human breast tumors, whereas SPCA1 levels were similar among all cell lines examined." (PMID 23594099, 2013). "Recent studies show that regions of the Ca2+ pump SPCA2 can activate ORAI1 and promote constitutive Ca2+ influx and phospho-protein signaling in MCF7 breast cancer cells, independently of Ca2+ store depletion." (PMID 22666335, 2012). "However, we cannot rule out the possibility that there may be other hidden ORAI1 SNPs which may associate with breast cancer development." (PMID 22778704, 2012). "The potential roles for specific Ca2+ channels in these pathways were assessed by siRNA-mediated silencing of ORAI1 and transient receptor potential canonical type 1 (TRPC1) channels in MDA-MB-468 breast cancer cells." (PMID 22666335, 2012). "Our results demonstrated that PMCA2, ORAI-1, and STIM1 were differentially expressed in the presence of Lr EV stimulation, suggesting a potential role for bacterial EVs in influencing the differentiation, migration, and metastasis of breast cancer cells." (PMID 40491474, 2025). "Unlike 2-APB, LOCI directly affected ORAI1 and ORAI3 at an extracellular-facing site, rather than intervening in the STIM1–ORAI1 interaction, and blocked Ca2+ entry in Jurkat T cells and a metastatic breast cancer mouse model." (PMID 38672434, 2024). "SOCE is co-regulated by ORAI1 and STIM1 and is strictly required for breast cancer cell migration." (PMID 36677874, 2023). "To evaluate whether canonical SOCE components including the Orai1, STIM1, and SARAF proteins, are correlated with breast cancer metastatic potential, we consulted The Cancer Genome Atlas Program (TCGA) NIH database using the GEPIA platform." (PMID 36982380, 2023). "Moreover, in breast cancer cells, TRPC6 was shown to be required for the Tg-induced translocation of ORAI1 and ORAI3 channels to the membrane." (PMID 37108424, 2023). "Despite an established role for ORAI1 in the basal calcium influx in MDA-MB-468 cells, KO and the rescue of ORAI1 in this breast cancer cell line did not significantly change the expression levels of the assessed Ca2+-regulated genes." (PMID 35682546, 2022). "Hence, we have further explored the possible effect of tunicamycin on Orai1 and STIM1 protein expression in MCF10A cells and MDA-MB-231 breast cancer cells." (PMID 36612199, 2022). "Our findings reveal a novel activation mechanism of Orai1 via direct interaction with NCL, which may lead to calcium homeostasis imbalance and promote the proliferation of breast cancer cells." (PMID 36109490, 2022).
breast cancer (continued). "We also performed this analysis in breast cancer MDA-MB-231 cells where the surface expression of Orai1 was not significantly altered by treatment with tunicamycin, which supports the lack of effect of tunicamycin on SOCE in these cells." (PMID 36612199, 2022). "NCL-meditated SOCE was required for the proliferation of breast cancer cells, so blocking the binding between NCL and Orai1-NT may lead to the reduction in calcium influx and inhibition of cancer cells proliferation." (PMID 36109490, 2022). "The relative importance of these different ORAI1 cell activation pathways has not yet been assessed in the regulation of gene expression in breast cancer cells." (PMID 35682546, 2022). "This study identified ORAI1 as a regulator of PTGS2 and IL6 expressions in basal breast cancer." (PMID 35682546, 2022). "In this aspect, Orai1, complexed with the SK3 channel, has been found to play a relevant role in breast cancer cell migration and inhibition of TRPC6/Orai1-mediated SOCE was found to attenuate breast cancer cell proliferation and migration." (PMID 33916304, 2021). "This suggests that STIM1 is not required to enhance SK3 currents by Orai1, similar as reported for breast cancer cells." (PMID 34944977, 2021). "Interestingly, in breast cancer cells of the luminal subtype (estrogen receptor positive (ER+) breast cancer cells), SOCE is strongly dependent on Orai3 channels, whose expression depends on estrogen receptor-α in these cells, with Orai1 playing a minor role." (PMID 34070268, 2021). "Analysis of the expression of Orai1 and Orai2 at the transcript level was carried out by qRT-PCR and revealed a greater expression of Orai1 mRNA transcript in all the breast cancer cell lines investigated as compared to non-tumor MCF10A cells (p < 0.01)." (PMID 35008277, 2021). "EGF-induced EMT in breast cancer cells results in the transcriptional up-regulation of the efflux transporter ABCC3 in a calcium-dependent manner, but independently of TRPM7 as well as of ORAI1 and STIM1 (component of the store-operated calcium entry pathway)." (PMID 34988012, 2021). "Moreover, we discovered clear co-localization of Orai1 and SK3 in specific spots of the cell membrane of HEK 293 cells, in line with previous reports showing their co-localization in breast cancer cells." (PMID 34944977, 2021). "Initially, we examined whether co-expression of Orai1 and SK3 in HEK 293 cells affects intracellular Ca2+ levels, as suggested for breast cancer cells." (PMID 34944977, 2021). "In the breast cancer cell line MCF-7, the accessory protein secretory pathway Ca2+-ATPase 2 (SPCA2), conventionally operating as a Golgi Ca2+ pump, has been identified to directly interact with the Orai1 channel at the cell surface." (PMID 33333945, 2020). "Furthermore, in breast cancer cell line MDA-MB-231, STIM1 and Orai1 remodel focal adhesion turnovers and are required for tumor invasion and metastasis." (PMID 32599788, 2020). "It remains so far elusive whether a co-expression of STIM1, Orai1 and SK3 in HEK 293 cells or overexpression of STIM1 in breast cancer cells alters the interplay of the Orai1/SK3 channel complex." (PMID 33333945, 2020). "Furthermore, the ORAI1 interaction with SK3, a small conductance calcium-activated potassium channel, has been correlated with invasion and metastasis in colon and breast cancer, respectively, via SigmaR1 chaperone." (PMID 32733237, 2020). "Assessment of microarray datasets indicates that ORAI1 levels are higher in basal breast cancers compared to non-basal." (PMID 30754719, 2019). "The canonical STIM1/Orai1-mediated SOCE mechanism has been found to be required for cell migration of several cancer types, including breast cancer, cervical cancer, gastric cancer, colorectal cancer, hepatocellular carcinoma, renal cell carcinoma, nasopharyngeal carcinoma, glioma, and melanoma." (PMID 31252656, 2019).
breast cancer (continued). "In conclusion, our results provide strong evidence for the impairment of phosphorylation-dependent Orai1 inactivation by AC8 overexpression in MDA-MB-231 cells, a mechanism that enhances Ca2+ influx, breast cancer cell migration (by supporting FAK activation), and cell proliferation." (PMID 31652779, 2019). "In breast cancer MDA-MB-231 cells, upregulation of Orai1 or STIM1 significantly increased the in vitro migratory capability and tumor metastasis potential in mice, whereas silencing of Orai1 or STIM1, as well as SOCE blockade with SKF-96365, attenuated these effects." (PMID 31252656, 2019). "In addition to Orai1, its close paralogue, Orai3, has been shown to mediate Stim1-triggered SOCE in oestrogen receptor positive (ER+) breast cancer and non-small cell lung adenocarcinoma cell lines." (PMID 30123430, 2018). "Motiani and coworkers confirmed that SOCE in triple negative MDA-MB-231 breast cancer cells is entirely dependent on STIM1 and Orai1, while in MCF7, SOCE is mediated by STIM1, STIM2 and Orai3 (overexpressed in this cell line), thus reporting important phenotypic differences between both cell lines." (PMID 30558192, 2018). "It should, however, be pointed out that Orai1 is constitutively open independently on Orai1, and therefore on ER Ca2+ levels, in both metastatic and non-metastatic breast cancer cells." (PMID 30123430, 2018). "A recent study has revealed that collagen 1 promotes in vitro breast cancer MCF7 cell survival through ERK1/2 phosphorylation and the overexpression and colocalization of Kv10.1 and Orai1 ion channels, an interaction that enhances constitutive Ca2+ influx in these cells." (PMID 30558192, 2018). "Orai1 and STIM1 were reported to promote cell proliferation, migration, invasion and apoptotic resistance in breast cancer, glioblastoma, prostate cancer, hepatocellular carcinoma, esophageal squamous cell carcinoma (ESCC) and clear cell renal cell carcinoma (ccRCC)." (PMID 25481035, 2015). "For instance, an increase in Stim1 and Orai1 transcripts and proteins has been described in oestrogen receptor-negative human breast cancer cell lines, while TRPC1 up-regulation in these cells is still controversial." (PMID 24603752, 2014). "Thirdly, the native SOCE pathway was found to be mediated by Orai3 in estrogen receptor-positive breast cancer cells whereas the canonical STIM1/Orai1 pathway was shown to be used by estrogen receptor-negative breast cancer cells." (PMID 24797725, 2014). "Although Orai1 silencing reduces Ca2+ influx in human breast cancer cell lines, no studies have directly assessed calcium influx mediated by this pathway in in vitro models of lactation." (PMID 24359162, 2013). "MDA-MB-468 breast cancer cells in the epithelial state have a high degree of non-stimulated Ca2+ influx through ORAI1, potentially due to alterations in ER Ca2+ reserves." (PMID 22666335, 2012). "Activation of ORAI1-mediated Ca2+ influx by other proteins has also been identified; this includes regulation by pre-STIM2 and SPCA2, the latter of which is a Ca2+ store-independent mechanism important in some breast cancers." (PMID 22666335, 2012). "In breast cancer cells, ORAI1 regulates processes important for carcinogenesis and is enriched in some breast cancer cell lines relative to non-tumorigenic breast epithelial cells." (PMID 22666335, 2012). "While Orai1 has been clearly shown to encode the SOC pore in many cells, a recent work showed that Orai3 is the SOC pore of estrogen receptor positive breast cancer cell lines, in contrast to estrogen receptor negative cell line which use Orai1." (PMID 21266088, 2011). "These patterns include elevated Fzd2 in metastatic breast cancer, increased ORAI1 in basal-like breast cancer (BLBC), high expression of Vangl2 and ROR1 in BLBC, and overexpression of Syndecan in BC generally." (PMID 40804731, 2025). "Notably, the overexpression of ORAI3, rather than ORAI1, plays a predominant role in prostate cancer and breast cancer." (PMID 38672434, 2024).
breast cancer (continued). "Our results indicate that Orai1 plays an essential role in the mammosphere formation and self-renewal ability, distinctive features of stem cells, as well as COX activity of the subpopulation of BCSC derived from the different breast cancer subtypes, more precisely in those derived from TNBC." (PMID 37945647, 2023). "To confirm the hypothesis that NCL promoted tumor growth by increasing calcium influx via interaction with Orai1, we subcutaneously implanted MCF-7 cells stably expression of NCL and negative control cells into nude mice to establish the subcutaneous breast cancer xenograft." (PMID 36109490, 2022). "Agonist-evoked Ca2+ signals through the activation of Orai1 also fine tune breast cancer cell functions as described in triple negative breast cancer cells where progesterone attenuates cell proliferation by a mechanism involving Ca2+ entry mediated by STIM2, Orai1, and TRPC1." (PMID 33916304, 2021). "However, SPCA2 is over-expressed in the plasma membrane of breast cancer cells, where it directly binds to and activates Orai1, independent of STIM1, and leads to enhanced Ca2+ entry and Ca2+-dependent proliferation." (PMID 32825277, 2020). "The effect of NCS‐1 silencing on cell death was phenocopied by silencing of ORAI1, a Ca2+ store‐operated Ca2+ channel that maintains Ca2+ levels in the endoplasmic reticulum Ca2+ store and whose expression was significantly positively correlated with NCS‐1 in clinical breast cancer samples." (PMID 31647602, 2020). "In breast cancer cells, however, Orai1 gating is independent on Stim1 and is not driven by ER Ca2+ store depletion; accordingly, Orai1 is activated by the Secretory Pathway Ca2+-ATPase, SPCA2, in MCF-7 cells and by a yet to be identified mechanism in MDA-MB-435 cells." (PMID 30123430, 2018). "To examine whether STIM1 and Orai1 are important molecular components involved in high salt mediated inflammatory responses, we used RNA interference (RNAi) to knock down STIM1 and Orai1 in MCF-7 and MDA-MB-231 human breast cancer cells." (PMID 29861863, 2018). "Here we show that in MDA-MB-468 breast cancer cells, both ORAI1 and TRPC1 silencing reduce non-stimulated Ca2+ influx; suggesting that altered activity of these channels may be a feature of EGF-induced EMT." (PMID 22666335, 2012). "The analysis of the expression ratio between the Orai1 variants indicates a greater expression of Orai1β in all the cell types investigated and, interestingly, a greater Orai1α/Orai1β expression ratio in MCF7 and MDA-MB-231 breast cancer cells than in non-tumoral MCF10A cells (p < 0.05; n = 6)." (PMID 31652779, 2019). "Consistent with the in vitro model, there was no consistent change in Orai1, STIM1, or STIM2 transcript levels in CAFs and NFs in paired breast cancer patient samples." (PMID 34208665, 2021). "In ER+ breast cancer cell lines, SOCE has been reported to be strongly dependent on Orai3 expression, while Orai1 knockdown in these cells was predominantly without effect, in contrast to the observations in triple-negative breast cancer cell lines." (PMID 34768857, 2021). "Here, we show that the breast cancer cell lines MCF7 and MDA-MB-231 exhibit enhanced expression of Orai1 and AC8 as compared to the non-tumoral breast epithelial MCF10A cell line." (PMID 31652779, 2019). "Nevertheless, constitutive Orai1-dependent Ca2+ entry has been reported in both non-metastatic (MCF-7) and metastatic (MDA-MB-435) breast cancer cell lines." (PMID 30123430, 2018). "Taken together, our data suggest that in MCF-7 and T-47D breast carcinoma cells, when seeded on collagen 1, DDR1 but not β1-integrin activates ERK1/2 promoting Kv10.1 and Orai1 overexpression leading to persistent MAPK signalling activation." (PMID 29872495, 2018). "We showed that SPCA2, but not SPCA1, traffics to the plasma membrane in the breast cancer derived MCF7 cell line, where it interacts with the store-operated Ca2+ channel Orai1 to elicit constitutive Ca2+ influx." (PMID 23840669, 2013).